IDH1 (isocitrate dehydrogenase (NADP(+)) 1)
Diseases named in the same sentence as IDH1 in open-access papers (continued):
Sharing a sentence is not in itself a finding about the gene and the disease.
tumor (continued). "The trial showed that patients with an IDH1(R132H)-specific immune response had an excellent two-year progression-free rate of 0.82, and this vaccine-induced response was associated with the presence of T-helper cells at the tumor site, thereby altering the tumor microenvironment." (PMID 41441679, 2025). "In addition, FBXw7 could increase the mutant IDH1 expression by preventing the SREBP1 degradation, while silencing FBXW7 results in IDH1-mutated tumor cells being highly responsive to radiotherapy." (PMID 38560498, 2024). "In the present study, we sought to investigate the association between NCF, executive functions, in particular, and IDH1 genetic mutation status in HGGs in order to shed light on the role that tumor proliferation rate may have on NCF impairment often seen in HGGs." (PMID 36970174, 2023). "Thus, 1 of the 13 patients on trial had a tumor with the IDH1 R132H mutation." (PMID 37218937, 2023). "Finally, the tumor volume mean was similar across IDH1 mutation groups (p > .05)." (PMID 36970174, 2023). "Multivariate Cox regression analysis disclosed the risk scores, neoplasm grade, age, and IDH1 status could be served as stand-alone prognostic elements for the TCGA team, and risk scores, neoplasm grade, and IDH1 status could be treated as stand-alone prophetic elements for the CGGA team." (PMID 37153540, 2023). "Interestingly, patients harbouring IDH1R132H mutated tumours have lower levels of genome-wide DNA methylation, an increased gene expression and the worst prognosis compared to patients affected by tumours with other IDH1/2 mutations." (PMID 37296846, 2023). "Although patients with IDH1 mutations generally have less invasive tumor characteristics than patients with wild-type IDH1 tumors, a higher WHO grade and repeated craniotomy might confer extensive neural network destruction, thus contributing to prolonged awakening." (PMID 37917280, 2023). "Tumor size and nCET could be used to determine IDH1 mutated tumors with an accuracy of 97.5%." (PMID 35330402, 2022). "However, only mutations in IDH1 and 2 are considered to be the drivers of tumor initiation." (PMID 35216362, 2022). "Thus, the IDH1/2 mutational status difference between the primary and secondary tumors could help differentiate the secondary tumor from the recurrence of the primary or de novo tumors." (PMID 35505351, 2022). "Additionally, the IDH1/IDH2 mutations characteristic of ODG tumours where CIC mutations are found result in the overproduction of 2‐hydroxyglutarate (2‐HG), which has the downstream consequence of widespread hypermethylation of CpG sites and histone tail residues." (PMID 34767259, 2022). "Interestingly, R-2HG was reported to be a tumor-promoted oncometabolite in PCa with IDH1 mutation." (PMID 35397614, 2022). "Mutations in IDH1 gene–encoded enzymes are expected to cause widespread disturbances of cellular metabolism, including DNA hypermethylation with subsequently increased tumor metabolism and degradation of HIF, leading to downstream inhibition of vasculogenesis- and angiogenesis-related signaling." (PMID 34671241, 2021). "In particular, a set of four CpGs (cg07425555, cg26969888, cg18547299, and cg24354933) may be of importance, as they show significant independent prognostic effects in both OS and DFS, after adjustments for age, gender, tumor grade, and IDH1 mutation in multivariate analysis." (PMID 34830454, 2021).
tumor (continued). "In addition, none of the traditional prognostic variables including patient age, tumour site, resection status and IDH-1 status was associated with patient survival (with individual Kaplan–Meier statistics of P = 0.396, P = 0.484, P = 0.855 and P = 0.643 respectively)." (PMID 32418115, 2020). "Several studies have shown that IDH1 mutation is a strong prognostic maker, and this may well be the most upstream genetic event in the tumourigenesis and may drive other genetic changes in tumour cells." (PMID 32382870, 2020). "This is probably because mutation in IDH1 gene may disrupt the function of IDH1 enzyme as the main catalyst for cellular metabolism, redox state and DNA repair in tumor cells, thus leading to the less progressive tumor and better survival of patients." (PMID 33282092, 2020). "Interestingly, all IDH1/2 mutated tumors showed an unifocal tumor growth pattern in our cohort." (PMID 34966832, 2020). "It is interesting to note that patients with prevalence of infiltrative tumor growing pattern, which means ΔT2T1 MRI index higher than 18 cm3, had a worse seizure outcome (66% of patient in Engel Class IB-IV) and expressed the IDH1-2 mutation in more than 90% of cases." (PMID 32046310, 2020). "However, combination of age and tumor volume revealed that the specificity with which IDH1 mutations in GBM may be identified increased to 93%." (PMID 31275753, 2019). "Circulating tumor DNA (ctDNA) are isolated from serum with next-generation sequencing or digital polymerase chain reaction (PCR) technique. ctDNA can be utilized to identify various mutations such as IDH1 mutation, 1p/19q-codeletion, MGMT methylation, and mutations in PTEN." (PMID 32642651, 2019). "Furthermore, specific tumor types show distinct predisposition to specific IDH1 or IDH2 mutations." (PMID 31727977, 2019). "In addition, the patients in our study were diagnosed based on the WHO 2007 Classification of Tumours of the Central Nervous System and IDH1 mutational status was only available for a subset of the patients, as it was not yet evaluated in routine clinical care." (PMID 31603915, 2019). "Studies focused on assessing the tumor volume, contrast enhancement status, Visually AcceSAble Rembrandt Images (Vasari) feature set, radiomics features or features that were derived via convolutional neural networks, among others and used these to train predictive models of IDH1 mutational status." (PMID 31881020, 2019). "Thus, the IDH1 mutation in the tumor cells renders the tumor in a higher excitatory state and may be directly involved in the pathogenesis of tumor-related seizures in LGGs." (PMID 29687214, 2018). "Thus, loss the enzymatic function of IDH1 in tumor cells could impair detoxification procedure, which may result in DNA damages and genes mutations." (PMID 30153799, 2018). "Coincidentally, we found that primary tumors with IDH1 mutations generally have lower levels of immune infiltrates compared with IDH1 wildtype tumors, including GBMs, which showed significantly greater numbers of immunosuppressive tumor-infiltrating cells, such as Tregs and TAMs." (PMID 29643764, 2018). "ANXA1 protein levels were also significantly higher in the HGG EVs compared with LGG EVs, which again may be associated with differences in tumour invasiveness between low- and high- grade tumours as well as the observed difference in IDH1 mutational status (Fig. 5b2)." (PMID 27770278, 2017). "Identification of IDH1 mutation status by IHC presents a useful tool for many diagnostic institutions where genetic testing can be burdensome and may be inaccurate, especially regarding tissue samples with low tumor cell content." (PMID 31548536, 2017). "Indeed, the majority of patients with IDH1 mutated gene underwent total tumor resection and therefore could allow better prognosis." (PMID 28785587, 2017). "The rapid detection of IDH1 mutation may also assist in determining the extent of tumor removal." (PMID 27877908, 2016).
tumor (continued). "Recent flux studies in tumor cells bearing isocitrate dehydrogenase 1 (IDH1) mutations indicate that these cells may be particularly dependent upon glutamine to fuel oxidative mitochondrial metabolism and thus may be responsive to inhibition of GLS or respiration." (PMID 25621173, 2015). "Since these data were based on whole genome sequencing that could overlook specific mutations, we performed targeted sequencing in the tumor (TCGA-B6-A1KF) with very high levels of 2-HG to look for the recurrent mutations found in other tumors in IDH1 and IDH2." (PMID 25091696, 2014). "Of interest, IDH1/2 mutated cancers accumulate 2-hydroxyglutarate in tumour tissue and release the molecule in blood, and the measurement of 2-hydroxyglutarate might be used as both a surrogate biomarker for IDH1/2 mutational status and a non-invasive test for the assessment of tumour burden in ICC." (PMID 24867389, 2014). "IDH1 mutation was frequently detected in LGGs, and it may result in tumor-related seizures." (PMID 24324372, 2013). "IDH1- mutations may thus set the scene for genetic and chromosomal instability leading to gene mutations and chromosomal events, which in themselves may influence tumor morphology." (PMID 22844452, 2012). "However, whether mutant IDH1 protein is required for maintaining IDH1 mutated tumor cell growth remains unknown." (PMID 22885298, 2012). "In vivo experiments confirm that ES more effectively suppresses tumor growth in IDH1-mutant xenografts." (PMID 41938504, 2026). "Our findings show that IDH1‐wild‐type tumours exhibit little difference in T values from the brain, while IDH1‐mutant tumours present significantly higher tumour T values compared with the brain." (PMID 41436375, 2026). "It was found that while IDH1‐wild‐type tumours present similar T1ρ values as the brain, IDH1‐mutant tumours exhibit significantly higher T1ρ values compared with the brain." (PMID 41436375, 2026). "There is support that hypermethylation of DNA damage pathways is unique to the IDH1 R132Q mutant; H3 histone hypermethylation studies with in vivo IDH1 R132H-expressing tumor models have suggested up-regulation of DNA damage response and cell cycle control." (PMID 40188944, 2025). "Even though direct studies on IDH1-mutant GSCs are limited, accumulating evidence suggests that both differentiated tumor cells and GSCs share this OXPHOS-centric metabolic profile, providing a common vulnerability." (PMID 40724998, 2025). "The combination of PD-1 inhibitors with FGFR2 inhibitors or IDH1 inhibitors aims to enhance immune responses and overcome tumour resistance mechanisms." (PMID 40861435, 2025). "Conversely, the absence of TNF-α can restore low acetylation levels at K115 on IDH1, resulting in the accumulation of reductive metabolites within tumor cells." (PMID 40906076, 2025). "This suggests that silencing DNA damage repair is likely an important strategy in both IDH1 R132Q-expressing tumor models." (PMID 40188944, 2025). "Case 2, a 60-year-old male, showed the tumor section presented with positive for 1p36/ 19q13 co-deletion, and the analyzed FFPE DNA sample was also positive for IDH1 gene, p.R132H (c.395G>A) variant." (PMID 40546613, 2025). "To probe the mechanism(s) behind the differences in tumor size in the IDH1 R132Q versus R132H and WT tumors, we used reduced representation bisulfite sequencing (RRBS) to analyze genome-wide DNA methylation in representative xenograft tumors." (PMID 40188944, 2025).
tumor (continued). "U87MG xenografts, which had more power than HT1080∗ xenografts due to higher tumor incidence, showed distinct clustering of IDH1 R132Q xenografts, with some clustering seen for WT and R132H tumors." (PMID 40188944, 2025). "Previous studies have demonstrated that elevated expression of SKP2 enhances glycolysis and facilitates tumor progression by promoting the degradation of isocitrate dehydrogenase 1 (IDH1)." (PMID 41241099, 2025). "Nevertheless, the significance of mutations in IDH1 and IDH2 proteoforms can differ based on the type of tumor and associated genetic changes." (PMID 41516249, 2025). "Accordingly, the build‐up of R‐2‐HG caused by IDH1/2 mutations decreases HIF‐1α levels and encourages tumor development, which includes astrocyte cancer." (PMID 40567251, 2025). "Despite the fact that the increase in 2-HG was small, it resulted in larger changes in related genes including IDH1 in the more aggressive cells, suggesting the power of this oncometabolite in tumor progression." (PMID 40871470, 2025). "Specifically, IDH1 establishes the CpG island methylator phenotype, which is characterized by extensive epigenetic changes that contribute to tumour pathogenesis." (PMID 40182999, 2025). "Further, IDH1 R132Q expression led to activation of several pro-tumor pathways, including those associated with EGFR and PI3K signaling reminiscent of lower grade mutant IDH1 tumors that progress to higher grade." (PMID 40188944, 2025). "This is perhaps unsurprising given the wide span in tumor weight and low n for WT IDH1-expressing HT1080∗ tumors." (PMID 40188944, 2025). "FDA-approved IDH1/2 inhibitors (ivosidenib, enasidenib) reduce D-2HG levels, restore differentiation, and enhance anti-tumor immunity in AML." (PMID 40734168, 2025). "The presence of D-2HG oncometabolite is strongly related to tumor cells harboring mutant IDH-1, as validated in both tissue metabolomics research and in vivo MR-spectroscopy evaluations in glioma patients." (PMID 41516249, 2025). "Including molecular biomarkers beyond MGMT, like IDH1/2 mutation status, ATRX loss, TERT promoter mutation, EGFR amplification, and 1p/19q co-deletion, can improve the model’s understanding of tumor biology." (PMID 41584616, 2025). "IDH1-mutant tumours exacerbate immune suppression through metabolic reprogramming, increasing the production of metabolites such as 2-HG, which inhibits the function of TET2 and reduces T-cell activation, contributing to resistance against ICIs." (PMID 40861435, 2025). "After this, we found that a large percentage of the differentially methylated sites were hypomethylated (n = 1262) in IDH1 R132Q-expressing U87MG tumor xenografts compared to both WT and R132H." (PMID 40188944, 2025). "High-risk LGG patients exhibited higher tumor mutation burden (TMB) and lower IDH1 mutation incidence." (PMID 40963614, 2025). "There was also IDH1 differential expression within tumors, with higher expression in the cellular tumor regions and lower levels at the invasive tumor edge." (PMID 40565099, 2025). "Transcriptome analysis shows increased expression of many pro-tumor pathways upon expression of IDH1 R132Q versus R132H, including transcripts of EGFR and PI3K signaling pathways." (PMID 40188944, 2025). "Despite these noteworthy findings, more efforts should be conducted to investigate the effects of MGD-C9 as a single agent or combined with inhibitors of BTK and IDH1, respectively, in xenograft tumor models." (PMID 41050081, 2025). "IDH1 inhibitors (e.g., ivosidenib) restore normal metabolic pathways, inhibiting tumour cell growth." (PMID 40861435, 2025).
tumor (continued). "IDH1-mutant tumours resist ICIs via epigenetic–immune crosstalk, whereas CPS1-deficient tumours disrupt the urea cycle to alter the pH of the TME." (PMID 40861435, 2025). "We validated this resistance phenotype by creating 53BP1 and REV7 knockouts in the parental IDH1-mutant tumor cells and by further characterizing the effects on the DNA damage response." (PMID 41357766, 2025). "The trial outcomes revealed that IDH1-vac effectively primed tumor-reactive T cell responses in HGG patients compared to control groups." (PMID 40661781, 2025). "Similar to the overall cohort, tumor cells were the most abundant cell type in the IDH1 cohort, followed by immune cells and fibroblasts." (PMID 39969434, 2025). "Histological evaluation of ROIs containing T cell cuffs revealed accumulation of gemistocytic cells in the surrounding tumor stroma that were positive for the IDH1-R132H antigen, demonstrating their neoplastic origin." (PMID 39880824, 2025). "Together, these tumor models showed that expression of IDH1 R132Q was associated with more catalytically efficient D2HG production, higher cellular, tumor, and serum levels of D2HG, and larger tumors compared to R132H." (PMID 40188944, 2025). "Specifically, when μNMR is combined with multiple tumor markers like EGFR, EGFRvIII, PDPN, and IDH1-R132H, the overall diagnostic accuracy has been elevated to over 90%." (PMID 39465690, 2025). "α-ketoglutarate is produced in the TCA cycle from isocitrate by IDH1 and has been shown to stimulate anti-tumor immunity." (PMID 40119362, 2025). "Jacob and colleagues reported IDH1-WT tumours with an aggressive growth phenotype to have a significantly higher success rate (96.4%) when compared to IDH1-mutant tumours (66.7%)." (PMID 39799339, 2025). "Age ≥ 65 years, preoperative KPS ≥ 80, post-concomitant CRT KPS ≥ 80, laterality, tumor location, IDH-1 mutant tumors, pMGMT methylated tumors or duration from resection-to-AEF and from CRT-to-AEF were not predictors for survival." (PMID 40067514, 2025). "Both genetic overexpression of SIRT1 and the use of pharmacological SIRT1-activating compounds inhibit the growth of IDH1-mutant tumor cells." (PMID 40710366, 2025). "Conventional tumor markers lack diagnostic accuracy; recent advancements in next-generation sequencing have identified actionable mutations, such as FGFR2 fusions and IDH1/2 mutations, enabling targeted therapies that improve survival." (PMID 40227772, 2025). "NCCN and ESMO recommend, at minimum, testing for fusions in FGFR2 and NTRK, mutations in IDH1 and BRAF, over-expression or amplifications of HER2/ERBB2, tumor-mutational burden (TMB), and microsatellite instability (MSI)." (PMID 39996880, 2025). "Metformin and phenformin, for instance, inhibit complex I of the electron transport chain and have demonstrated selective toxicity in OXPHOS-dependent IDH1-mutant tumor cells." (PMID 40724998, 2025). "Understanding the unique DNA and histone methylation features among different tumor tissue and among different IDH1 and IDH2 mutants remain important areas of research." (PMID 40188944, 2025). "We conducted serial xenograft tumor studies with patient-derived IDH1-mutant HT1080 fibrosarcoma cells, isolating tumor populations exhibiting resistance to PARPi treatment." (PMID 41357766, 2025). "Finding distinct methylation and transcription patterns when comparing HT1080∗ and U87MG xenografts was unsurprising, as this has been reported in tumors and tumor models of mutant IDH1-driven cancers." (PMID 40188944, 2025). "Additional mutations impacting genes like HIF1A, IDH1, or tumor suppressors further introduce variability in metabolic wiring between CRC tumor cells and microenvironments." (PMID 39273409, 2024).